BCL2 (BCL2 apoptosis regulator)
Diseases named in the same sentence as BCL2 in open-access papers (continued):
Sharing a sentence is not in itself a finding about the gene and the disease.
breast carcinoma (continued). "Taken together, BCL2 might be the most potential target involved in the constructed MUC14-related ncRNA-mRNA network in breast cancer." (PMID 34828282, 2021). "Some studies suggested that the absence of BCL2 was correlated with poorly differentiated tumors (breast carcinomas) or associated with an unfavorable prognosis (soft tissue tumors)." (PMID 34572445, 2021). "Through gain and loss of function and rescue experiments, we confirm that MIR200CHG regulates the expression of tumor-associated proteins CDKN2A, cyclin D1, cyclin E1, BCL2, BAX, MMP1, MMP2, and MRP1 by binding YB-1, thereby promoting breast cancer proliferation, invasion, and resistance." (PMID 34272387, 2021). "Therefore, the balance between pro- and anti-apoptotic members of this family determines the cellular fate; in this case, the increased bax/bcl2 ratio confirmed the apoptosis of breast cancer cell lines that was previously observed." (PMID 34067547, 2021). "Furthermore, we demonstrated that the efficacy of siBCL-2 NKExos is directly dependent on the BCL-2 expression in breast cancer cells." (PMID 34063475, 2021). "The biomarkers with the most evidence as highlighted in this paper which may have prognostic implications on breast cancer in older women include and are under reported in the current literature include: BCL2, cyclin E, EGFR, LKB1, MUC1 and CKs." (PMID 34165702, 2021). "Bcl-2 proteins, are anti-apoptotic and promote breast cancer formation and progression." (PMID 33902604, 2021). "Besides being studied as a prognostic marker, BCL-2 is investigated as a therapeutic target in ER+ breast cancer." (PMID 34063475, 2021). "BCL2 expression could be utilized to assess the prognosis of breast cancer patients in clinical settings." (PMID 34099764, 2021). "Dysregulation of apoptosis due to imbalances in BAX/BCL-2 levels may result in breast cancer pathogenesis." (PMID 33708254, 2021). "BCL2 expression could be utilized to predict prognosis of operable breast cancer patients in clinical settings." (PMID 34099764, 2021). "Leptin activates the JAK-STAT breast cancer pathway leading to c-MYC and BCL2 expression mediated cell growth and proliferation, whereas estrogen may regulate the development of estrogen dependent breast cancers." (PMID 34225729, 2021). "Besides, HHT can also induce breast cancer cell apoptosis by regulated the expression of apoptosis-related protein like Bax/Bcl-2, Caspase3/Caspase9 and PARP." (PMID 33867824, 2021). "In addition, BCL-2 also mediated multidrug resistance in human breast cancer, lung cancer, colon cancer, etc.." (PMID 33623790, 2021). "It was shown that HMGA2 silencing promotes apoptosis by reducing antiapoptotic Bcl-2 expression in ovarian cancer and we found that HMGA2 derepresses the expression of Bcl-2 by inhibiting miR-34a in breast cancer, thereby promoting the Bcl-2 antiapoptotic pathway." (PMID 33668453, 2021). "In addition, our data pointed out that the expression of anti-apoptotic marker, Bcl-2 was lost when treated with PAMAM dendrimers suggesting that PAMAM dendrimers induce apoptotic activity in breast cancer cell lines." (PMID 34093999, 2021). "Therefore, the aim of the present case-control study was to investigate the association of BCL-2 (-938C>A), BAX (-248G>A), and HER2 Ile655Val polymorphisms with breast carcinoma risk in Indian population." (PMID 33708254, 2021). "In breast cancer, apoptosis following paclitaxel treatments is boosted by miR-7-5p, miR-542-3p, miR-621, and miR-5195-3p via directly modulating BCL-2, survivin, F-box protein 11 (FBXO11), and eukaryotic translation initiation factor 4A2 (EIF4A2), respectively." (PMID 33066509, 2020).
breast carcinoma (continued). "Moreover, studies with several different breast cancer cell lines indicated that the relative amounts of Bcl-2 and Bax proteins are highly predictive of the sensitivity to apoptosis, with the increase of Bax/Bcl-2 ratio, in mammary tumor cells." (PMID 32046125, 2020). "The opposite result was also reported such that the deficiency of METTL3 could inhibit the proliferation of breast cancer cell line MCF-7, by m6A-level-decreasing-mediated Bcl-2 up-regulation." (PMID 32766145, 2020). "In luminal breast cancer cells, we have shown that CAFs conditioned-media-induced apoptotic resistance to BCL-2/BCL-xL inhibitors could be completely reversed with a BH-3 mimetic targeting MCL-1 (A1210477)." (PMID 33080792, 2020). "Bcl-2 has been postulated to be both oncogenic and tumor-suppressive in specific cell types or conditions and reported to be a favorable prognostic factor in breast cancer." (PMID 33198064, 2020). "In addition, in breast cancer, there are distinct abnormalities in the apoptotic pathway such as Bcl-2 overexpression, which confers resistance to chemotherapy." (PMID 33080824, 2020). "Furthermore, MGE enhanced the expression of Bax, cleaved caspase-3, and cleaved PARP, proapoptotic factors, while reducing the expression of Bcl-2, an antiapoptotic factor, in tumor tissues of human breast cancer." (PMID 32774407, 2020). "We also examined whether phosphorylation of BCL-2 at ser70 enhances BCL-2 antiapoptotic functions in breast cancer cell." (PMID 32929329, 2020). "The study also explores the role of BCL-2 as a novel targeted therapy for breast cancer." (PMID 33414642, 2020). "Downregulation of BCL2 and cyclin D1 enhanced cisplatin sensitivity in breast cancer cell lines." (PMID 32660222, 2020). "In breast cancer, the prognostic role of BCL2 is still controversial." (PMID 33160404, 2020). "Strikingly, ERα + breast cancer cell lines have limited sensitivity to BCL-2 inhibitors." (PMID 33308268, 2020). "Thus, by neutralizing anti-apoptotic proteins, the E.A./CDDP combination modified the Bax/Bcl-2 and Bax/Bcl-xL ratio and promoted apoptosis in breast cancer cells." (PMID 32033130, 2020). "Furthermore, the incubation of curcumin with MCF-7 human breast cancer cells in vitro resulted in the downregulation of the apoptosis suppressor gene Bcl-2 by increased expression of miR-16 and miR-15." (PMID 32823812, 2020). "The active constituents of the herbs modulate innumerable molecular events that comprise regulators of intracellular signaling such as vascular endothelial growth factor, nuclear factor-κB, and Bcl-2 that are integrally involved in the development and progression of breast cancer." (PMID 32823812, 2020). "It was suggested that usnic acid-induced BCL2 downregulation might be regulated by miR-185-5p in BT-474 breast cancer cell line." (PMID 32366289, 2020). "Similarly, lutein promoted apoptosis in MDA-MB-231 and MCF-7 breast cancer cells with increased caspase-3 activity and downregulated Bcl-2 and poly-ADP ribose polymerase." (PMID 32859058, 2020).
breast carcinoma (continued). "The decrease of the poly-ubiquitylated forms of Bcl-2 in cells depleted of BRCA1, independently of PRMT1 expression, also confirmed that cytosolic BRCA1 might control the stability of Bcl-2 in breast cancer cells." (PMID 32764667, 2020). "We observed a significantly decreased expression of p-Akt, p-PI3K, p-mTOR and subsequent decreased expression of FOXO, Cyclin D1 and Bcl-2 following levobupivacaine treatment which correlated with decreased breast cancer cells proliferation and increased apoptosis." (PMID 32807213, 2020). "Finally, in vitro cell viability experiments have indicated effective interactions between Cu (II) dendrimers and pro-apoptotic siRNAs: Mcl-1 and Bcl-2 in breast cancer cells." (PMID 32748821, 2020). "The survival of breast cancer cells significantly decreased after incubation with G4@IONPs and exposure to an alternating magnetic field (AMF) due to apoptosis and elevation of Bax (Bcl-2 associated X)/Bcl-2(B-cell lymphoma 2) ratio." (PMID 33266461, 2020). "Whether cytosolic BRCA1 controls apoptotic pathways in breast cancer cells by interacting with antiapoptotic proteins such as Bcl-2 is also an issue to be resolved." (PMID 32764667, 2020). "In addition, MGE reduced the tumor mass of human breast cancer by regulating the expression of apoptosis-related proteins, such as Bcl-2, Bax, cleaved caspase-3, and cleaved PARP, in a whole body system." (PMID 32774407, 2020). "Moreover, our results for the first time demonstrated that Nar markedly enhanced the expressions of BAX, a major pro-apoptotic mediator, and furthermore, reduced the expression of Bcl-2 as the main anti-apoptotic factor in breast cancer cells." (PMID 33680016, 2020). "Furthermore, we found that lncUSMycN depletion resulted in significantly lower expression of Bcl-2 and higher expression of E-cadherin in breast cancer cells." (PMID 31102367, 2019). "Moreover, during studying about the effects of IL-32θ on breast cancer cell proliferation, we have found that Bcl-2, an anti-apoptotic factor which has been proposed as a prognostic marker, was totally repressed by IL-32θ in vitro (data not shown)." (PMID 31126309, 2019). "On the other hand, our previous studies on chemoprevention, using the same rat model, demonstrated a significant correlation of an increase in Bax/Bcl-2 and caspase-3 expression in mammary carcinoma cells in vivo after dark fruit peel, oregano, and clove bud administration." (PMID 30970626, 2019). "A growing body of data suggests that Mcl-1 may play a strategic role in ERα+ breast cancers, a breast cancer subtype that expresses Bcl-2, Bcl-xL and Mcl-1." (PMID 31595181, 2019). "To study whether simultaneous neutralization of Bcl-2 and Bcl-XL by the prototype BH3 mimetic ABT-737 reactivates Myc-associated apoptosis in vivo, we utilized an autochthonous WapMyc mouse model of breast cancer." (PMID 30728358, 2019). "Moreover, the knockdown of LINC00673 enhanced bax expression and reduced bcl-2 and cyclin D1 levels in breast cancer cells, confirming that LINC00673 is involved in apoptosis and cell cycle progression." (PMID 31623640, 2019). "Differentially expressed BCL-2 genes in breast cancer subtypes." (PMID 31825969, 2019).
breast carcinoma (continued). "Interestingly, activation of upstream kinase ERK leads to Bcl-2 suppression in breast cancer cells treated with resveratrol resulting in apoptotic cell death." (PMID 31618928, 2019). "For example, in MDA-MB-231 breast cancer cells, the antitumor effect of c-phycocyanin was mediated by induction of apoptosis trough upregulation of Fas protein levels of and cleavage of caspase-3, while downregulation of Bcl-2 protein was observed." (PMID 30621025, 2019). "Importantly, Mcl-1 is a key survival factor used by several cancers to promote cell survival upon inhibition of Bcl-2 and Bcl-xL, including ER+ breast cancers." (PMID 31595181, 2019). "Moreover, metformin enhanced tamoxifen-mediated induction of apoptosis in breast cancer cells via the bax/bcl-2 apoptotic pathway and the AMPK/mTOR/p70S6K growth pathway." (PMID 31780804, 2019). "A lot of studies have proved that positive BCL2 shows better prognosis in breast cancer 41-43." (PMID 31777591, 2019). "However, BCL2, which is present in a majority of breast cancer cell lines SVMs, was present in only one gene signature derived from TCGA data." (PMID 30652029, 2019). "This proapoptotic effect was caused by the activation of the intrinsic signaling pathway, in particular owing to the profound down-regulation of the antiapoptotic molecules Bcl-2 and Bcl-xL, an effect that was previously suggested as a mechanism of action of copanlisib in breast cancer cells." (PMID 30962952, 2019). "Similarly, the JNK/Bcl-2/Beclin1 pathway is thought to play a key role in the induction of apoptosis and autophagic cell death in breast cancer cells by the co-treatment of curcumin and berberine." (PMID 31505816, 2019). "We next examined whether the AMPK and BCL-2/BCL-XL co-targeting strategy triggers MYC-dependent apoptosis in human breast cancer tissue." (PMID 30728358, 2019). "Many studies in human breast cancer have explored the protective effects of Bcl-2 positivity in luminal breast cancers, i.e., which are positive to Estrogen Receptor alpha (ER) and/or Progesterone Receptor (PR), and have found that Bcl-2 positivity is associated with a better outcome." (PMID 30630524, 2019). "Notably, up to 70% of ER+ breast cancers express Bcl-2, although Bcl-2 is expressed at low levels in other breast cancer subtypes." (PMID 31595181, 2019). "Preclinical studies validated the use of BCL-2 inhibitors to enforce tumor cell death in human luminal breast cancer justifying a Phase 1b Study of Bcl-2 inhibition with ABT-199 in combination with tamoxifen in metastatic ER-positive breast cancers (ISRCTN98335443)." (PMID 30631150, 2019). "Some studies have shown that resistance occurs via up-regulation of pro-survival members of the BCL-2 family, including BCL-2 and MCL-1, although BCL-2 is commonly associated with ER positivity and better prognosis in breast cancer, being a favorable prognostic marker." (PMID 30720718, 2019). "Besides, forced expression of HOXA1 in human mammary carcinoma cells resulted in increased proliferation and decreased apoptotic cell death in a Bcl-2-dependent manner." (PMID 31507632, 2019). "This suggests that miR-148a may serve as a potential tumor suppressor in breast cancer by silencing pro-survival BCL-2." (PMID 31590453, 2019). "Other than indirectly modulating the Bcl-2 family to induce MOMP, γ-T3-treated MDA-MB-231 breast cancer cells have been found to show a direct disruption of mitochondrial membrane potential independent from Bax/Bcl-2 ratio alteration and poly(ADP-ribose) polymerase (PARP) cleavage." (PMID 30654580, 2019). "Thus, high expression levels of MYC and anti-apoptotic BCL-2 proteins are common features in breast cancer." (PMID 30728358, 2019). "Bcl-2 expression has been described in feline mammary carcinomas, in a study where 13 out of 15 carcinomas were Bcl-2 positive, however without associated survival analysis." (PMID 30630524, 2019).
breast carcinoma (continued). "MiR-16-5p was among the first downregulated miRNAs identified in chronic lymphocytic leukemia due to frequent deletions and moreover gained wider attention as a regulator of anti-apoptotic BCL2 in prostate and breast cancer as well as breast cancer development." (PMID 30658505, 2019). "Therefore, the data suggested that compound 4 inhibited breast cancer progression through inducing apoptosis On the basis of these results, the protein ratio of Bax and Bcl-2 increased compared to the control group (**p < 0.01)." (PMID 30467293, 2018). "We first determined the effect of selective BCL2 proteins inhibition on mitochondrial activity in our previously characterised MCF7 breast cancer cells overexpressing either BCL2 (MCF7-BCL2) or BCL(X)L (MCF7-BCL(X)L), or transfected with the corresponding empty vector (MCF7-pSFFV)." (PMID 29899841, 2018). "Here, we assumed that P/G-NPs could act like tamoxifen to modulate Bcl-2 levels in breast cancer cells, and lead to cell apoptosis." (PMID 30405089, 2018). "EGCG applied to MD-MB-231 human breast cancer cells led to reduced cell growth and apoptosis related to stimulation of Bcl-2-associated X protein (BAX), cleavage of poly (ADP-ribose) polymerase protein (PARP) and reduction of Bcl-2 expression." (PMID 29558948, 2018). "It is also true that Gli inhibitor GANT-61 treatment could also decreased Bcl2 and increased proapoptic factor Bax in other breast cancer cell lines MCF and MDA-MB-453." (PMID 29734730, 2018). "Furthermore, Tamoxifen treated ER (+) breast cancers often increase BCL-2 and BCL-XL levels which leads to a decreased acute tumor response and ultimately to a long-term resistance to Tamoxifen." (PMID 29983888, 2018). "ERα+ breast cancers frequently overexpress anti-apoptotic Bcl-2, Bcl-xL, and Mcl-19–12." (PMID 29343814, 2018). "Interestingly, MCL1 mRNA levels were found to inversely correlate with BCL2 upon analysis of two large independent breast cancer data sets." (PMID 29339815, 2018). "Our study supported HPI-1 treatment could alter the gene expression of Bcl2 and Bim to induce apoptosis in breast cancer cells." (PMID 29734730, 2018). "In addition, the expression of Bcl-2 predicts the efficacy of adjuvant chemotherapy in breast cancer patients." (PMID 29876007, 2018). "These conflicting reports, in addition to a lack of studies observing the role of other anti-apoptotic factors in ERα+ breast cancer resistance, led us to further explore the role of Bcl-2, as well as Bcl-xL and Mcl-1, in response of ERα+ breast cancers to endocrine inhibition." (PMID 29343814, 2018). "In addition, the anti-apoptotic mitochondrial proteins Bcl-2 and Bcl-xl were decreased in ZR-75-30 breast cancer cells infected with siPAICS." (PMID 30097015, 2018). "Researchers showed that MET reduced migration and invasion of cancer cells in tamoxifen-resistant breast cancer cells and in combination with tamoxifen synergistically inhibited proliferation of ER-positive breast cancer via Bax/Bcl-2 and AMPK/mTOR/p70S6K pathways." (PMID 30483391, 2018). "Furthermore, downregulation of Bcl-2 enhances the effects of chemotherapeutic agents in human breast cancer cells." (PMID 29876007, 2018). "Furthermore, we demonstrate that BCL2 inhibitors are synthetically lethal in breast cancer cells when combined with the glycolysis inhibitor 2DG, a finding that we also observed when cells were grown in 3D spheroids." (PMID 29899841, 2018).